S100P (S100 calcium binding protein P)
Diseases named in the same sentence as S100P in open-access papers (continued):
Sharing a sentence is not in itself a finding about the gene and the disease.
tumor (continued). "Furthermore, S100P expression was a predictor of survival in HCC patients with high tumor stage or ETR (P = 0.0026 and P = 0.0002, respectively)." (PMID 23785431, 2013). "Heterogeneous to focal S100P expressions in 10∼50% tumor cells were seen in 33 cases." (PMID 23785431, 2013). "S100P was expressed in a small number of tumor cells in 131 cases." (PMID 23785431, 2013). "Diffuse S100P expressions in more than 50% tumor cells were seen in 9 cases." (PMID 23785431, 2013). "S100P regulation by the PGE2/EP4 receptor signaling pathway may therefore constitute a feedback regulatory mechanism by which tumor cells perpetuate growth and migration during carcinogenesis." (PMID 23166536, 2012). "S100P induces the expression of cathepsin D, an aspartyl protease, that takes part in the proteolytic degradation of the extracellular matrix, hence it increases the invasive potential of the tumor." (PMID 23166536, 2012). "Moreover, its direct implication in cancer biology has been proposed on the basis of the experimental data obtained with S100P-transfected tumor cells in vitro and in vivo as well as of the data from various gene array studies." (PMID 18282279, 2008). "We speculate that CTSE and S100P establish a delicate “balance” within the tumor microenvironment." (PMID 41301873, 2025). "Thus, downregulating the expression of S100P may enhance T cell immune activity and achieve anti-tumor immunotherapy objectives." (PMID 37853345, 2023). "Hence, targeting S100P may offer a promising strategy to convert the tumor immunologically “hot” and trigger an anticancer immune response." (PMID 37853345, 2023). "To determine whether S100P correlated with tumor immunity, we conducted comprehensive analyses." (PMID 34654352, 2021). "High S100P expression reduced the infiltration of macrophages and CD4 + T cells, thereby promoting tumor immune escape, and decreased the expression of common immune inhibitors, suggesting that S100P inhibition may improve the expression of treatment targets to improve the efficacy of immunotherapy." (PMID 34654352, 2021). "Anti-S100P was investigated in this present study because its cellular expression may interact with growth factors and their receptors, leading to several effects such as tumour proliferation." (PMID 33238953, 2020). "Moreover, differences between cancer models may also arise as S100P can act extracellular and/or intracellularly, crosstalking with a variety of signaling pathways, which can be differently activated depending on the tumour origin." (PMID 31767037, 2019). "Another gene set was the S100 family including S100A11, S100P and S100A6, which mediate tumor progression and metastasis through their roles in cell motility, invasion, and angiogenesis." (PMID 40018643, 2025). "In pan-cancer analysis, S100P and S100A8 exhibited significantly altered expression in 8 and 12 tumor types, respectively." (PMID 40224483, 2025). "Immunohistochemically, tumor cells are positive for AE1/AE3, EMA, cytokeratin (CK), brachyury, focally S-100P, MNF116, OSCAR, and glypican 3, as per the study by Rekhi." (PMID 39233954, 2024). "Results show that the expression levels of S100P and S100A14 were significantly (p < 0.001) higher in the tumor tissue compared to the normal tissues." (PMID 39594999, 2024). "S100P has frequently been identified as an upregulated gene in PDAC48,53–59 and both the gene and the S100P protein are plausible therapeutic targets in PDAC, with cancer cell apoptosis and anti-tumor activity being consequences of targeting." (PMID 38342953, 2024). "Intriguingly, the extracellular S100P has the ability to bind RAGE; thereby, it can enhance tumor progression, resistance and migration." (PMID 37511575, 2023). "Key subtype markers, SPP1 and S100P, were mapped across the UMAP plot to obtain valuable insights into their differential expression and potential roles in tumor progression." (PMID 38239853, 2023).
tumor (continued). "S100-derived peptide (ELKVLMEKEL) was found to compete for the RAGE site required to bind ligands, such as S100P, S100A4, and HMGB1, and reduced RAGE-mediated NF-κB activation, inflammation, tumor growth, and metastasis in different cancer cells." (PMID 35956875, 2022). "According to our scRNA-seq data, most of the tumor cells either expressed S100P (23.95%) or SPP1 (60.05%), while only 10.01% and 5.98% tumor cells showed double negativity or double positivity, respectively." (PMID 35347134, 2022). "To test the impact of S100P expression on metastasis formation in vivo, we injected S100P- overexpressing SW480/S100P cells into the spleen of SCID beige mice and evaluated tumour growth and liver metastasis." (PMID 35597866, 2022). "S100A2, S100P and MMP12 were all over expressed in tumor tissues based on paired (P < 0.01) and unpaired expression analysis (P < 0.001)." (PMID 35831362, 2022). "However, S100P induction may be considered an important step during the early stage of LUAD; furthermore, its low expression during advanced stages seems to be associated with tumor progression." (PMID 36530971, 2022). "Protein expression of MACC1 and S100P in the sections correlated significantly (N = 27) and we observed an increase of both MACC1 and S100P staining in tumour tissue with metachronous metastasis." (PMID 35597866, 2022). "Of the overlapping set of proteins, the levels of WFDC2, S100P, CD55, MDK, THBS2, and MFAP2 were more than 2-fold higher in PDAC compared with tumor-adjacent tissue in our data." (PMID 36923555, 2022). "S100P, S100A2 and MMP12 were expressed higher in tumor tissues, compared with normal tissues (P < 0.001), while the opposite was true for DEFA5 expression (P < 0.05)." (PMID 35831362, 2022). "Next, we were interested if there is an overlap of tumour-promoting target genes of MACC1 and S100P, when ectopically expressed in SW480 cells." (PMID 35597866, 2022). "S100P was found to be overexpressed in HCC tissues and correlated with advanced tumor behavior and poor prognosis." (PMID 33815482, 2021). "The expression level of S100P was negatively correlated with B cells, CD8+ T cells, CD4+ T cells, neutrophils, and dendritic cells but positively correlated with tumor purity in LUAD." (PMID 34745947, 2021). "Compared with para-cancer tissues, the expression levels of S100A4/S100A6/S100A10/S100A11/S100A13/S100A14/S100P were higher in HCC tissues, while the expression levels of S100A8/S100A9/S100A12 were decreased in tumor tissues." (PMID 33815482, 2021). "S100P binds to the receptor for advanced glycation end-products (RAGE) and activates cellular signaling to mediate tumor growth and metastasis." (PMID 34200172, 2021). "Combination of gene expressions for uroplakin II, S100P, NKX3.1 and PSA approached 100% accuracy in tumor classification both in the training and validation sets." (PMID 33762601, 2021). "S100P secretes matrix metalloproteinase 9 (MMP9) and regulates the invasion of PC cells into the lymphatic endothelial monolayer, thereby promoting tumor cell invasion and metastasis." (PMID 33173782, 2020). "Other studies found that the expression of S100P in LUAD is up-regulated, and the interaction between extracellular S100P and receptor for activated glycation end products (RAGE) contributes to tumor development." (PMID 32819300, 2020). "Immunohistochemical evaluation of both S100P and E-cadherin in a TMA encompassing 333 tumours revealed high expression in 62.7 and 64% of the cases, respectively." (PMID 31767037, 2019). "S100P, CXCL11, and SRY (Sex Determining Region Y)-Box 11 (SOX11) display higher expression in tumor samples." (PMID 27857161, 2016). "There was also a significant increase in the expression of MMP13 (P = 0.0169), S100P (P = 0.0234) and COL10A1 (P = 0.024) compared with expression in the corresponding non-tumor tissue." (PMID 27857161, 2016).
tumor (continued). "An in vivo assay demonstrated that SOX9-promoted peritoneal metastasis was blocked by S100P knockdown, indicating that up-regulation of S100P expression at least partially accounts for the function of SOX9 in promotion of tumor progression in vivo." (PMID 26009899, 2015). "After adjustment, tumor size, tumor differentiation, AJCC stage, SOX9 expression, and S100P expression were identified as covariates." (PMID 26009899, 2015). "The mean percentage positivity for biomarkers in tumour vs. normal tissue was as follows: for KOC 74% vs. 0.4%; for S100P 75% vs. 0.3%; for mesothelin 75% vs. 4%; and for MUC1 75% vs. 18% (p < 0.0001 for all tumour vs. normal comparisons)." (PMID 25071419, 2014). "The mean percentage of positive carcinoma cells in tumour tissue was 74% for KOC, 75% for S100P, 73% for mesothelin and 75% for MUC1." (PMID 25071419, 2014). "Extracellular S100P binds to the cell surface receptor for advanced glycation end products (RAGE) and activates its downstream signaling cascade to meditate tumor growth, drug resistance and metastasis." (PMID 25084534, 2014). "Our study indicates the expression of the S100P protein is a novel independent predictor for poor prognosis in HCC, and it is also an unfavorable prognostic predictor in HCC patients with high tumor stage or ETR." (PMID 23785431, 2013). "Most of these genes (MUC12, S100P, GSTT1, USP9Y, MSLN and so on) are involved in tumor initiation, progression or metastasis." (PMID 23787019, 2013). "On the other hand, activation of genes involved in cell survival, angiogenesis and tumor progression, such as VEGF, S100P, MALAT-1 and different stress response genes, raises questions." (PMID 17880733, 2007). "Specifically, the level 3 classifier shows strong correlations among genes like KRT5, S100A7, KRT16, S100P, and LY6D, while the level 6 classifier exhibits similar patterns with GPR17, RGR, and NPPA, highlighting the complex interplay of genes in tumor subtype classification." (PMID 40802546, 2025). "We hypothesize that the S100P+ cholangiocytes observed in HCC may represent an aberrantly proliferative and activated population induced by tumor microenvironmental stimuli." (PMID 40474968, 2025). "Immunopathological tests have detected γH2AX, a marker of double-stranded DNA damage, in various areas, including areas of bile ducts without tumor invasion, and the expression of S100P in BilIN, which indicate precancerous and early-stage cancer lesions." (PMID 38514507, 2024). "One study analyzed 144,878 cells from 14 pairs of iCCA tumor and non-tumor liver tissues using single-cell RNA sequencing and found differential expression of S100P and SPP1 in iCCA portal macrotubules (iCCAphl) and peripheral microtubules (iCCApps)." (PMID 39290697, 2024). "Four microarray datasets provided validation results that supported the notion that tumor tissues exhibited higher expressions of S100P as compared to non-tumor samples." (PMID 37853345, 2023). "Future studies will be necessary to define the functional significance and underlying mechanisms of other tumor supportive cytokines/chemokines (i.e., IL1A/B, LIF, G/M-CSF and CXCL2/3) and inflammatory proteins (i.e., S100P and S100A9) in mediating XIST regulation of tumor growth and CSC activity." (PMID 36922677, 2023). "However, in tumor tissues, correlations were observed between S100A7 and S100A14 (R = 0.47), and S100P (R = 0.56), suggesting crosstalk between these different S100s in tumors." (PMID 37627239, 2023). "For the remaining seven S100P- iCCAs (P09, P10, P12, P13, P14, P15, and P19), they expressed iCCApps markers NCAM1 and CDH2, which were mutually exclusive with the expression of S100P, confirming the different origins of these tumor cells." (PMID 35347134, 2022).
tumor (continued). "Our analysis of tumours from previously non-metastasised CRC patients revealed that primary tumours of patients with metachronous metastasis during the disease have a higher S100P expression than tumours from patients without metastatic relapse." (PMID 35597866, 2022). "First, we stained MACC1 and S100P protein levels in tumour sections of CRC patients without synchronous metastasis at the time of diagnosis (UICC I–III) by IHC." (PMID 35597866, 2022). "As both intracellular S100P expression levels and high abundance of extracellular S100P can promote tumour progression and metastasis, we tested if the MACC1-mediated expression of S100P in CRC cells also leads to an increase in extracellular S100P protein levels." (PMID 35597866, 2022). "S100P + SPP1− iCCAphl had less CD3+ T and CD56+ NK cells, but more CCL18+ macrophage infiltration than S100P-SPP1 + iCCApps, indicating its dampened anti-tumor immune response that may contribute to the higher invasive potential." (PMID 35347134, 2022). "Here, the authors perform single cell RNA-sequencing from 14 pairs of iCCA tumours and non-tumour liver tissues and propose S100P and SPP1 as markers for patient classification." (PMID 35347134, 2022). "There were not correlations between S100P and NK either in paracancerous tissues (p = 0.214) or tumor tissues (p = 0.808)." (PMID 34805160, 2021). "Tumor immunohistochemical analyses were presented as follows: Inhibin-α (-), ER (-), Vimentin (mesenchyme +), CK7 (+), CK19 (+), CK20 (−), CEA (−), MUC-1 (+), MUC-5AC (+), MUC-6 (+), MUC-2 (−), S-100p (focal+), and Ki-67 (12% +)." (PMID 33592896, 2021). "Interestingly, by characterizing these immune components in situ we found that S100P is a driver for tumor cells to induce TAM migration and M2 polarization in the immunosuppressive tumor niche." (PMID 34805160, 2021). "Comparison of expression profiles of ET (≤40 years) and LT (≥55 years) yielded few genes that are unique between the two groups, 7 genes B4GALNT1, S100P, KLK4, HIST3H2A, DRD4, PCSK1N, and BAPX1 were significantly overexpressed in early-onset tumours compared to late-onset tumours." (PMID 31292488, 2019). "Conversely, abnormal DNA methylation is related to the occurrence of several human diseases, with many studies showing the role of aberrant DNA methylation in the activation of tumor promoter genes (e.g., MAGE, S100P) and silencing of tumor suppressor genes (e.g., VHL, MLH1) in various cancers." (PMID 30833961, 2019). "Further, in patients bearing E-cadherin negative tumours, S100P expression aggravates patients outcomes, namely their overall survival, indicating that our candidate molecule would be a good therapeutic target for these patients." (PMID 31767037, 2019). "According to Kaplan-Meier analysis, the overall survival time of patients with CRC staged I–III with S100P protein expression was significantly shorter when compared to those without the expression of S100P protein in the tumour tissue." (PMID 26880885, 2016). "Interestingly, 4 of the top 5 up-regulated proteins in tumor TIF were all S100 family members, including S100P (ratio = 40.9), S100A9 (ratio = 19.0), S100A8 (ratio = 5.3) and S100A12 (ratio = 4.5)." (PMID 27216119, 2016). "Therefore, we concluded that SOX9 induces the expression of S100P, which consequently activates its direct target, RAGE, and phosphorylates ERK1/2, subsequently leading to EMT, which promotes tumor invasion and metastasis." (PMID 26009899, 2015). "The expression levels of KOC, S100P and mesothelin were high in tumour tissue compared with normal tissue." (PMID 25071419, 2014). "We found that HCC patients with high tumor stage and S100P expression had a lower 5-year survival rate than high tumor stage HCCs without S100P expression." (PMID 23785431, 2013).
tumor (continued). "Additionally, several tumor related genes, including Maspin, WFDC1, SLPI, S100P, and PDGFRB, were shown to be differentially expressed in MGC803 cells in response to latexin expression." (PMID 21466706, 2011). "However, in the tumor array, positive correlations were observed between S100A14 and S100A2 (R = 0.50), S100A4 (R = 0.55), S100A6 (R = 0.45), S100A7 (R = 0.47), S100A11 (R = 0.65), S100A16 (R = 0.57) and S100P (R = 0.66)." (PMID 37627239, 2023). "However, the significance of S100P expression in our tumour panel was higher in locally advanced tumours (UICC Stages II–III), leaving the prognostic value of S100P in the earlier tumour stages to be evaluated in a larger cohort before its implementation in the clinical decision." (PMID 35597866, 2022). "However, in these immunocompromised systems, S100P affected cell/tumour growth in contrast to the syngeneic, immunocompetent, mammary system of the present experiments in which the S100P mutants did not affect tumour incidence." (PMID 34680103, 2021). "In NK cells, S100P was not localized, but highly expressed in tumor tissues." (PMID 34805160, 2021). "Strikingly, within the group of patients bearing E-cadherin negative tumours, those expressing S100P had the worst prognosis of the cohort, substantiating our cellular studies and supporting its oncogenic role as previously suggested for a number of cancers, including GC." (PMID 31767037, 2019). "Ultimately, we propose that S100P targeting therapies may benefit the subgroup of patients bearing E-cadherin negative tumours." (PMID 31767037, 2019). "Further analysis showed that the majority of HCC cases with the β-catenin mutation had low tumor stage and a lower incidence of ETR, regardless of the presence or absence of S100P expression (7 of 13 versus 15 of 19 and 2 of 9 versus 2 of 17, respectively, both P>0.05)." (PMID 23785431, 2013). "Moreover, our findings suggest that the expression of S100P augments the metastatic potential of HCCs, resulting in high tumor stage, and increases the severity of the disease course, contributing to poor prognosis in HCC patients with high tumor stage or ETR." (PMID 23785431, 2013). "Therefore, those that did not express S100P or expressed S100P in less than 1% of the tumor cells were defined as the negative group (132 cases)." (PMID 23785431, 2013). "Recent studies have shown that DNA methylation, IL-6, bone morphogenic protein, prostaglandin E (PGE)/EP4, glucocorticoid, and non-steroidal anti-inflammatory drugs could regulate S100P expression during tumor progression." (PMID 23216986, 2012). "The results showed that hGF and PTX3 expression was downregulated and S100P expression was upregulated in LUAD, and that the expression of all the three was correlated with immune cell infiltration, suggesting that all the three gene could promote tumor progression." (PMID 34745947, 2021). "The association between ESR1 and S100A8 and S100A9 expression levels was positive in Basal patients but negative in Her2, Luminal A, and Luminal B. S100P and S100A14 expression levels were higher in tumor tissues than in normal ones." (PMID 39594999, 2024). "Immunohistochemically, the tumor cells were positive for desmin, MYOD1 and SMA, focally positive for myogenin, while negative for h-caldesmon, SOX10 and S100P." (PMID 35642345, 2023). "We also examined the 825 significantly changed genes differentially expressed in ALDH+ CSCs, which identified S100P and S100A9 as the top two genes most significantly inhibited in ALDH+ CSCs but not ALDH- bulk tumor cells upon XIST KD." (PMID 36922677, 2023). "Since MACC1 expression in SW480 cells or in xenograft tumours is not elevated upon S100P expression, the higher metastasis formation of SW480/S100P tumours is solely a consequence of S100P overexpression in these cells." (PMID 35597866, 2022). "Sections from exemplary tumours without metachronous metastasis showed low MACC1, as well as low S100P IHC staining." (PMID 35597866, 2022).